XIAP (X-linked inhibitor of apoptosis)
Diseases named in the same sentence as XIAP in open-access papers (continued):
Sharing a sentence is not in itself a finding about the gene and the disease.
cancer (continued). "The simulation showed that cytosolic Bcl-2, XIAP, caspase 3 and other protein expression regulated when a cancer cell would become sensitized to TRAIL via Yoda1 and the degree of sensitization." (PMID 31685811, 2019). "Both XIAP and Survivin, diminish apoptosis induced by anti-cancer agents through a decrease of caspase-3 activation." (PMID 30754643, 2019). "Many anti-apoptotic proteins such as C-FLIP, MCL-1, and XIAP inhibit apoptosis through disruption of extrinsic/intrinsic apoptotic pathways in cancers." (PMID 31238539, 2019). "Bcl‐2, Bcl‐XL, survivin, and XIAP have been involved in the resistance of cancer cells to chemotherapy." (PMID 31361391, 2019). "Hypothetically cancer cell XIAP is involved in an immunomodulatory process that mitigates T-cell antitumor activity as XIAP is described to be involved in NFκB signaling." (PMID 31151416, 2019). "X-linked inhibitor of apoptosis (XIAP), an endogenous caspase inhibitor, blocks the execution of apoptosis and is an important survival factor in cancer cells." (PMID 31284594, 2019). "Pretreatment of cancer cells with quercetin inhibited the phosphorylation Akt and IKKβ, and led to the suppression of NF-κB and anti-apoptotic protein xIAP." (PMID 31528215, 2019). "XIAP downregulation also re-sensitized resistant cancer cells to cisplatin treatment and led to an increase in apoptotic cell population." (PMID 31652965, 2019). "X-linked inhibitor of apoptosis protein (XIAP), a key regulator in the progression of human cancers." (PMID 31624242, 2019). "The molecular signature behind our observation opens important implications to further dissect the role of XIAP and for the development of novel XIAP antagonists for cancer treatment." (PMID 31505859, 2019). "In conclusion, the data presented here reveal a novel ATM-p85α-XIAP-PTEN network with translational applications in cancer." (PMID 31635307, 2019). "Since XIAP can inhibit apoptosis by interacting with caspase-3, it is a key target to enhance a number of modalities of pro-apoptotic cancer therapy." (PMID 31248045, 2019). "The recognition motif specifically recognizes the X-linked inhibitor of apoptosis protein (XIAP), which is overexpressed in cancer cells." (PMID 31649241, 2019). "We further examined the potential mechanisms by which XIAP facilitates EMT process in cancer cell lines." (PMID 31548877, 2019). "In both EC9706 and TE13 cell lines, knockdown of XIAP decreased the migration of cancer cells by inhibiting EMT process through regulating the TGF-β signaling pathway, pinpointing a regulatory role of XIAP in migratory process upon TGF-β activation." (PMID 31548877, 2019). "The targets of these molecules were related to cell proliferation (X-linked inhibitor of apoptosis protein, XIAP; Protein Kinase A, PKA), cell signaling (HRAS), resistance to chemotherapy (heat shock protein 27, Hsp27), or cancer stroma (TGFβ2)." (PMID 31470511, 2019). "XIAP was identified as a tumor activator because of its role on proliferation and apoptosis in cancer cells." (PMID 31548877, 2019). "Here, the authors make a drug delivery system that is activated within the cell and exploits XIAP expression to cleave a linker region, resulting in the self-assembly of the system and drug release within cancer cells." (PMID 31649241, 2019). "XIAP is overexpressed in a variety of human cancers and mediates resistance to chemotherapeutic drugs in specific subgroups of patients (reviewed in 12)." (PMID 31410190, 2019). "It is known that bcl-2, cIAP-2, livin, survivin and XIAP are the anti-apoptotic markers that prevent cancer cells undergoing apoptosis." (PMID 31521140, 2019).
cancer (continued). "AEG-35156, a 19-mer phosphorothioate ASO targeting XIAP, was developed for the potential treatment of cancer by lowering the apoptotic threshold and inducing cell death, as well as enhancing the cytotoxic action of chemotherapeutic agents." (PMID 31284594, 2019). "H-scores of p68 and RelA followed similar trends with H-scores of Bcl-2, Bcl-xL, Survivin and XIAP in both normal and carcinoma samples." (PMID 31351496, 2019). "X-linked inhibitor of apoptosis protein (XIAP) has been found to be a promising therapeutic molecular target in Middle Eastern BC and other cancers." (PMID 30647872, 2018). "Both these anti-apoptotic proteins were described in turn to modulate NF-κB activation, reinforcing the idea that survivin and XIAP confer a broad advantage for cancer cells." (PMID 29547633, 2018). "Several “SMAC mimetic” molecules are being developed as cancer therapies aiming to sensitize tumor cells to apoptosis by antagonizing cIAP1/2 and XIAP activity." (PMID 30552344, 2018). "In another recent report, new derivatives of embelin that have aromatic groups linked to the benzoquinone core via the Suzuki–Miyaura reaction were synthesized and tested for its XIAP inhibitory activity in cancer cells." (PMID 29522451, 2018). "TLR4-transient knockdown cells had a reduction of intrinsic expressions of IL-6, IL-8 and XIAP in both cancer cells." (PMID 29486738, 2018). "Study’s also demonstated that interaction of XIAP and MDM2 inhibit the ability of MDM2 as self-association and self-ubiquitination, which upregulate the MDM2 protein stabilization and cancer cell surivival." (PMID 29464049, 2018). "This led to the development of a series of small molecule Smac mimetics that neutralize X-linked IAP (XIAP), cellular IAP1 (cIAP1) and cIAP2 to enhance cancer cell susceptibility to apoptosis." (PMID 29946223, 2018). "XIAP is an important member of the inhibitors of apoptosis (IAP) family that is involved in cancer-cell survival." (PMID 29522451, 2018). "It is thus proposed that during PTX elimination of cancer cells, it activates inflammatory mediators, in particular IL-6, IL-8 and XIAP from cancer cells, and these cytokines can then aggravate anti-apoptosis via the TLR4 signaling pathway." (PMID 29486738, 2018). "Several publications have highlighted the involvement of XIAP in chemoresistance acquisition in various cancers, including ovarian cancer." (PMID 30552344, 2018). "On the other hand, both qPCR and western blot assays confirmed that NKILA suppressed activation of several NF-κB target genes including CCND1, TWIST1, MMP9 and XIAP, all of which play vital roles in cancer growth and metastasis." (PMID 29348395, 2018). "XIAP, a well-described suppressor of cell death has also been shown to be highly overexpressed in many forms of cancer." (PMID 28666324, 2017). "XIAP, an important regulator of cell apoptosis pathway, has been found to be aberrantly expressed in various types of human cancers." (PMID 29190902, 2017). "Increasing researches have focused on XIAP inhibition to develop new therapies for cancer prevention and treatment." (PMID 29221164, 2017). "For example, endothelial cells isolated from a tissue sample obtained from a cancer patient’s tumor biopsy can be analyzed to determine the intracellular XIAP and PARP levels." (PMID 29258506, 2017). "As studies demonstrate that balance of XIAP and caspases/Smac/DIABLO determine the efficacy of chemotherapy, decreasing the level of XIAP is considered as an effective strategy to enhance the chemotherapy-induced apoptosis in cancer cells." (PMID 29371950, 2017).
cancer (continued). "XIAP is overexpressed in a number of cancer cell lines, and its overexpression correlates with increased resistance to chemotherapeutic drugs, including inhibitors of mitosis." (PMID 27927753, 2017). "Inhibitor of apoptosis (IAP) proteins (IAPs), including the X-linked IAP (XIAP) and cellular IAP-1 and 2 (cIAP-1/2), participate in cancer cell progression." (PMID 28036295, 2017). "This method was then applied to characterize the efficacy of various candidate anti-cancer compounds that target the XIAP:NFκB survival pathway." (PMID 28460441, 2017). "Specifically, the expression levels of the apoptotic protein caspase-3 and antiapoptotic protein XIAP were upregulated and downregulated, respectively, in Danshen-extract-treated cancer cells." (PMID 29284481, 2017). "Activation of AKT is involved in regulation of XIAP expression in many cancers including hematological malignancies." (PMID 28704451, 2017). "Downregulation of XIAP has been shown to sensitize drug-resistant cancer cells to chemotherapeutic agents-induced apoptosis." (PMID 28057023, 2017). "Other reported targets of miR-24 include proapoptotic (FAF-1, Caspase-9, Bim, and Apaf-1) and cell cycle proteins; miR-24 was also shown to regulate XIAP, reducing the threshold for apoptosis in cancer cells." (PMID 28061479, 2017). "Elevated expression of XIAP mediates the resistance of cancer cells to chemotherapeutic drugs, as well as radiotherapy." (PMID 28057023, 2017). "Due to their multidimensional roles in the progression of cancers, XIAP and its family members have emerged as attractive candidates for anti-cancer therapy." (PMID 28057023, 2017). "We observed a remarkable increase in XIAP protein cleavage in drug combination-treated DU 145 cancer cells compared to the incubation with individual agents." (PMID 29182622, 2017). "As nitrosylation of XIAP is inhibitory, denitrosylation by Trx is expected to promote anti-apoptotic signaling, rendering the cancer cells resistant to chemotherapy or radiation." (PMID 28081246, 2017). "In going forward, it will be useful to assess the efficacy of retro-inverse SMAC peptides in alternative cancer cells types with varying levels of XIAP expression." (PMID 28424988, 2017). "X-linked Inhibitor of Apoptosis Protein (XIAP), a member of anti-apoptotic protein family, suppresses apoptosis of cancer cells via interaction with apoptotic inducers." (PMID 29371950, 2017). "XIAP is the most potent and most studied inhibitor of caspases among human cIAP family, and promising therapeutic target in cancer treatment." (PMID 29182622, 2017). "Because of the anti-apoptotic effect as well as its over-expressing potential in cancer cells as compared to its normal counterparts, XIAP is emerging as a potential therapeutic target for the management of cancer." (PMID 28893228, 2017). "Other than inhibiting apoptosis, XIAP is involved in many cellular functions related to the cancer malignancy." (PMID 28057023, 2017). "Aberrant expression of XIAP was found in a variety of human cancers, including esophageal carcinoma, acute leukemia, non-small cell human lung cancer, ovarian carcinoma, bladder cancer, and several other carcinomas." (PMID 29221164, 2017). "Smac/DIABLO is an effective apoptotic inducer in cancer cells, which can be inactivated by interacting with XIAP." (PMID 29371950, 2017). "For example, XAF1 has been shown to inhibit proliferation and to induce the apoptosis of cancer cells as it negatively regulates the caspase-inhibiting activity of XIAP." (PMID 28184177, 2017). "Increased XIAP expression has been shown to correlate with chemoresistance of cancer cells to drugs and radiotherapy." (PMID 29221164, 2017).
cancer (continued). "This function provides new insight into the mechanisms behind the XIAP regulating the cancer cell growth." (PMID 28057023, 2017). "Critically, XIAP expression is up-regulated in a number of different types of cancers, some of which are intrinsically resistant to chemotherapy." (PMID 28424988, 2017). "The importance of XIAP antagonism in cancer treatment is additionally demonstrated by its ability to overcome TRAIL resistance." (PMID 28424988, 2017). "In particular the expression pattern of XIAP indicates distinct gene expression patterns between carcinomas of the floor of the mouth and oral tongue cancer." (PMID 28486965, 2017). "Poorly differentiated carcinomas showed significantly elevated levels of XIAP than well differentiated carcinomas." (PMID 29190902, 2017). "We established CD133+ stem-like cells from DAOY and D283MED cell lines, and found that these CD133+ cancer stem-like MB cells express robust levels of XIAP and cIAP1/2." (PMID 27537345, 2016). "Recently, it is been shown that TQ induces synergistic effect on TAM via XIAP mediated Akt regulation in both ER+ and ERbreast cancer cells." (PMID 27540530, 2016). "XIAP is a direct inhibitor of caspase activity, while increased expression of BAG3 in cancers is linked to the maintenance of cell survival, treatment resistance, and increased metastasis." (PMID 26799209, 2016). "Knockdown of c-FLIP together with XIAP was sufficient to induce significant cell death in resistant cancer cell lines." (PMID 27048361, 2016). "MiR-410 expression levels were found to be reduced, while XIAP mRNA levels were increased in cancer when compared to normal tissues." (PMID 27259577, 2016). "Studies demonstrate that restoration of the XIAP/Smac balance in chemotherapy resistant cancer cells can re-establish apoptosis." (PMID 26071313, 2015). "Some retrospective studies indicate that overexpressions of NF-κB downstream effector proteins (e.g., VEGF, MMP-9, cyclin-D1, and XIAP) in cancer cells portend poorer survival for HCC patients." (PMID 26539482, 2015). "Among the eight human homologues of IAP family, survivin and XIAP have received more attention in recent years, with more than 30 survivin- and XIAP-based anti-cancer preparations undergoing clinical trials." (PMID 26496035, 2015). "Because its overexpression is associated with cancer formation and progression, drugs antagonistic to XIAP have shown promise as cancer therapeutic agents." (PMID 25686839, 2015). "In our earlier study, we found that TRIP-Br1 inhibits the apoptosis of cancer cells by stabilizing XIAP, a potent apoptosis inhibitor." (PMID 26334958, 2015). "As an uPA inhibitor highly prevalent in the ECM, PN1 is in a position to impede this process and therefore mitigate XIAP expression and ultimately apoptosis in cancer cells." (PMID 25686839, 2015). "XIAP IRES increased colony formation of either SK-N-SH or SH-EP1 cells expressing MDM2 but not the SH-EP1 cells with MDM2 knockdown, suggesting that the effect of XIAP IRES on cancer cell growth is MDM2-dependent." (PMID 25888903, 2015). "In fact, it is reported that upregulated XIAP is detected in many cancer patients and that a high level of XIAP expression is associated with resistance to chemotherapy and a poor prognosis." (PMID 25888903, 2015). "In fact, blocking or disrupting the interaction between the MDM2 RING protein and XIAP IRES RNA by a specific antisense leads to inhibition of cancer cell growth and increased apoptosis." (PMID 25888903, 2015). "Our previous report showed that TRIP-Br1 inhibits cancer cell death by stabilizing XIAP through direct binding with it." (PMID 26334958, 2015).
cancer (continued). "In previous in vitro analyses, it was reported that both ACA and rhAFP mediates their anti-cancer effects through the NF-κB signalling pathway and by disrupting XIAP-caspase interaction respectively." (PMID 26158863, 2015). "XIAP and cIAP1 are amplified in various cancers and here we have shown that overexpression of these proteins induces autophagy." (PMID 25669656, 2015). "Antiapoptotic proteins such as Bcl-2 and XIAP prevent loss of MMP and expression of caspase-3 activation leading to inhibition of apoptosis during cancer treatment." (PMID 26539482, 2015). "We examined the effect of XIAP IRES on cancer cell apoptosis and death induced by knockdown of XIAP." (PMID 25888903, 2015). "XIAP and cIAP1 are two members of the inhibitors of apoptosis protein family whose expression is elevated in different cancers." (PMID 25669656, 2015). "To further examine the effect of caspase-3 during apoptosis, we transfected an XIAP construct into cancer cells to antagonize caspase-3 activation." (PMID 26469967, 2015). "XIAP and cIAP1 are highly expressed in almost all of a series of 60 human cancer cell lines studied." (PMID 25669656, 2015). "Our studies demonstrated a mutual regulation of MDM2 protein and XIAP mRNA in cancer cell growth and disease progression." (PMID 25888903, 2015). "Specific inhibition of these caspases by the XIAP protein suggests that this molecule is critical for regulating sensitivity to anti-cancer treatment." (PMID 25888903, 2015). "Upon apoptosis stimuli, AKT, its active form p-AKT and XIAP are very often downregulated to block proliferation and enhance apoptotic mechanisms as observed upon treatment with PS2Aa1 on various cancer cells." (PMID 26263002, 2015). "More recently, survivin expression was also shown to enhance the metastatic potential of cancer cells by promoting, together with XIAP, NF-kB-dependent transcription and secretion of fibronectin." (PMID 25204429, 2014). "Among the marine compounds, lactone spongistatin induces the degradation of XIAP, an anti-apoptotic protein that is overexpressed in chemoresistant cancer cells." (PMID 24807532, 2014). "Our results demonstrated that ISO is a promising chemopreventive agent via upregulating mkp-1 mRNA stability, which is distinct from its cancer therapeutic effect with downregulation of XIAP and cyclin D1 expression." (PMID 24797581, 2014). "Our results provide a significant insight into understanding of biological significance of the increased nuclear XIAP expression in cancer cells and poor prognosis of clinical patients with nuclear XIAP overexpression." (PMID 25216527, 2014). "Giving this crucial role in regulating cell death and cancer, XIAP proteins have been very attractive targets for cancer treatment." (PMID 25574358, 2014). "This suggests that additional clinical studies are required to identify those cancer patient subgroups that benefit from XIAP-targeted therapy." (PMID 25120954, 2014). "In summary, we demonstrated here that cancer cells transfected XIAP deletion of RING domain led to cyclin e transcription and protein expression via binding with and modulation of the E2F1 transactivation." (PMID 25216527, 2014).